DKK1 (dickkopf Wnt signaling pathway inhibitor 1)
Diseases named in the same sentence as DKK1 in open-access papers (continued):
Sharing a sentence is not in itself a finding about the gene and the disease.
acute coronary syndrome (6 papers, 2013 to 2025). Signs and symptoms related to acute ischemia of the myocardium secondary to coronary artery disease. "In accordance with our findings, the DKK-1 levels in serum have been reported to be a significant predictor of MACEs in patients after acute coronary syndrome." (PMID 36291617, 2022). "It has been reported that circulating DKK-1 levels vary by time in patients after an acute coronary syndrome." (PMID 36291617, 2022). "Studies have shown that DKK1 plays a role in cardiovascular disease, not only by correlating with the severity of acute coronary syndromes, but also by promoting disease progression." (PMID 33867842, 2021). "We have previously shown that DKK1 may contribute to inflammation in vascular cells; is a predictor of adverse outcomes in acute coronary syndrome; and may have adverse metabolic effects, which could be relevant in postmenopausal women." (PMID 31197079, 2019). "However, no study has evaluated the association of DKK-1 and acute coronary syndrome (ACS)." (PMID 23359112, 2013). "In the present study, we assessed the plasma DKK-1 levels in patients in a stable condition after discharge, but not the levels measured during acute coronary syndrome." (PMID 36291617, 2022).
acute myocardial infarction (6 papers, 2017 to 2024). Necrosis of the myocardium, as a result of interruption of the blood supply to the area. "There is a positive correlation between DKK-1 expression and the recovery period following acute myocardial infarction (MI)." (PMID 30699965, 2019). "Wnt ligands have been shown to be upregulated alongside their feedback regulators Dkk1 and Dkk2 as a response in mouse models with induced cardiac injuries such as myocardial infarction." (PMID 30526659, 2018). "In our study, we also found that ADMA and ET-1 were positively correlated with DKK1 levels in plasma from healthy controls, unstable angina pectoris and acute myocardial infarction patients (P<0.05)." (PMID 28703797, 2017). "However, the causal relationship between DKK1, PDGF-B, and the risk of acute myocardial infarction (AMI) is yet to be established." (PMID 38175715, 2024).
bone metastasis (6 papers, 2014 to 2023). Transfer of a neoplasm from its primary site to bones. "Serum levels of the Wnt-inhibitor DKK1 have also been identified as elevated within patients with bone metastasis from NSCLC." (PMID 32751181, 2020). "Our group has previously reported higher levels of Dkk-1 in PB plasma from untreated advanced BCPs compared to HVs even before bone metastasis was observed, which could partially explain the increase number of OCPs in BM of BCPs." (PMID 36890825, 2023). "Predictive value of serum DKK1 in the subgroups of bone metastases, such as in those with solitary bone metastasis, multiple bone metastasis, isolated bone metastases, additional visceral or cerebral metastases, stage N0 + N1, stage N2 + N3, stage T1 + T2 and stage T3 + T4 were further investigated." (PMID 29108326, 2017). "Other agents in clinical trials - in particular, neutralizing antibodies against sclerostin and DKK1 and activin A-blocking reagents - could show similar efficacy in bone metastasis-specific clinical settings." (PMID 25757219, 2014). "To examine whether RSPO2/RANKL-DKK1 signaling is specific to bone metastasis patients, we next examined the serological RSPO2, RANKL, and DKK1 levels in benign breast lump patients (n = 9), primary BCa patients (n = 28), and bone metastasis BCa patients (n = 10)." (PMID 34847079, 2022).
brain tumors (6 papers, 2010 to 2024). "This conclusion is consistent with reports that Dkk-1, an inhibitor of the Wnt signaling pathway, negatively regulated cellular resistance to cisplatin in brain tumors, head and neck cancer, and HCC." (PMID 38794215, 2024). "A screening of 73 brain tumors, however, revealed that no obvious mutations of DKK-1 were found in these brain tumors." (PMID 20920327, 2010).
endothelial dysfunction (6 papers, 2016 to 2025). In vascular diseases, endothelial dysfunction is a systemic pathological state of the endothelium (the inner lining of blood vessels) and can be broadly defined as an imbalance between vasodilating and vasoconstricting substances produced by (or acting on) the endothelium. "On the other hand, an overexpression of DKK-1 is associated with cardiovascular risk, including inflammation, endothelial dysfunction, and atherosclerotic development." (PMID 36291617, 2022). "Evidence indicates that the overexpression of DKK-1 is markedly associated with reduced cell proliferation, endothelial dysfunction, and concomitant platelet activation." (PMID 30699965, 2019). "DKK-1 is linked not only with the effects of TNFα on joints in RA but also with platelet-mediated endothelial cell activation, endothelial dysfunction in T2DM, vascular calcification, and premature myocardial infarction." (PMID 28553649, 2017). "Additionally, in diseases with a high CV risk, such as T2DM, elevated DKK-1 levels have been observed compared to healthy controls, correlating with endothelial dysfunction and platelet activation." (PMID 40299461, 2025). "In addition, elevated plasma concentrations of DKK-1 are associated with macrovascular disease in patients with type 2 DM18, as well as endothelial dysfunction and platelet activation." (PMID 27320846, 2016).
epilepsy (6 papers, 2010 to 2023). A brain disorder characterized by episodes of abnormally increased neuronal discharge resulting in transient episodes of sensory or motor neurological dysfunction, or psychic dysfunction. "Moreover, expression of the epilepsy-related molecule DKK-1 was first induced in neurons of the olfactory cortex in an in vivo epilepsy model, which may explain the susceptibility of the olfactory cortex." (PMID 37033907, 2023). "Previous studies have shown that Dkk1 can promote cell death in models of AD, epilepsy, and ischemia and affect adult neurogenesis by modulating the generation of immature neurons in the adult DG." (PMID 27593374, 2016). "For these reasons, Dkk-1 antagonists or GSK3β inhibitors could be promising therapeutic candidates for epilepsy." (PMID 33202963, 2020).
esophageal adenocarcinoma (6 papers, 2019 to 2025). A malignant tumor with glandular differentiation arising predominantly from Barrett mucosa in the lower third of the esophagus. "Compared to healthy esophageal tissue, the gene expression of Dickkopf 1 (Dkk1) has been shown to be elevated in Barrett’s esophagus." (PMID 34199909, 2021). "Both findings, the increase in Dkk1 and the decrease in Wnt3a support Wnt-independent β-catenin activation in Barrett’s esophagus." (PMID 30841855, 2019). "DKK1 has been studied both in human specimens and cell lines of esophageal adenocarcinoma." (PMID 39795613, 2025). "High levels of S-DKK1 could be especially observed in patients suffering from esophageal adenocarcinoma which may promote the hypothesis of a crucial role of DKK1 in inflammation." (PMID 34638464, 2021). "Interestingly, this tumor-inducing function of DKK1 in cell lines of esophageal adenocarcinoma was shown to be independent of b-catenin as opposed to esophageal squamous cell lines and Barret esophagus cell lines." (PMID 39795613, 2025).
Insulin resistance (6 papers, 2011 to 2025). Increased resistance towards insulin, that is, diminished effectiveness of insulin in reducing blood glucose levels. "DKK1-overexpressed mice also showed significant insulin resistance, suggesting that DKK1 may cause insulin resistance through activation of the JNK signaling and thus exacerbate liver steatosis." (PMID 36410795, 2023). "As expected, the HFD-induced insulin resistance in sh-DKK1 mice was significantly decreased, whereas the GTT was markedly increased in OE-DKK1 mice compared with GFP-NC controls." (PMID 36410795, 2023). "Using HFD-induced NAFLD mice model, we conducted knock-down or OE of DKK1 specifically in the liver and found that DKK1 was a key player of steatosis and insulin resistance, and DKK1-driven steatosis is CD36-dependent through ERK-PPARγ signaling." (PMID 36410795, 2023). "Obviously, it needed further validation to clarify the detailed role of CD36 in DKK1-induced insulin resistance." (PMID 36410795, 2023). "Higher DKK-1 levels were observed in patients with older age, a current smoking habit, lower insulin resistance reflected by the HOMA-IR index, lower HDL cholesterol, lower eGFR, higher triglycerides, higher platelet count, higher CRP, and higher NT-proBNP." (PMID 36291617, 2022). "Because insulin resistance is associated with PI3K–AKT-FOXO1 axis, the phosphorylated AKT and FOXO1 were examined, and it was found that DKK1 decreased phosphorylation of AKT (Ser473) and FOXO1." (PMID 36410795, 2023). "Furthermore, liver-specific OE or knock-down of DKK1 in HFD mice and gene manipulations in hepatocyte cell lines revealed that up-regulated DKK1 aggravates hepatic steatosis and insulin resistance." (PMID 36410795, 2023). "Increased DKK1 in hepatic steatosis contributes CD36-mediated fatty acid uptake and insulin resistance." (PMID 36410795, 2023). "Obese subjects with insulin resistance (higher HOMA-IR and lower oral glucose insulin sensitivity index) had higher expressions of DKK1, DKK2, sclerostin, and sFRP-1 but lower expression of osteogenic microRNA and β-catenin." (PMID 37569816, 2023).
metabolic syndrome (6 papers, 2020 to 2026). A cluster of metabolic risk factors for CARDIOVASCULAR DISEASES and TYPE 2 DIABETES MELLITUS. "In the present study, dyslipidemia status, characterized by hypertriglyceridemia and low HDL cholesterol levels, was associated with plasma DKK-1 levels." (PMID 40422877, 2025). "As DKK1 is a natural antagonist of the Wnt signaling and the Wnt pathway is reportedly involved in metabolic syndromes such as NAFLD, the expressions of key genes in Wnt signaling were examined in DKK1 knockout HepG2 cells treated with FFA." (PMID 36410795, 2023). "Both tocotrienols also prevented the increase in sclerostin and DKK-1 levels in the animals with metabolic syndrome, which negatively regulate the activation of Wnt/β-catenin by preventing the binding of Wnt ligands to the frizzled receptor, lipoprotein receptor-related protein 5/6." (PMID 36144598, 2022). "In rats with metabolic syndrome, AT lowered RANKL, SOST, DKK-1 and fibroblast growth factor-23 level." (PMID 34790038, 2021).
pancreatic adenocarcinoma (6 papers, 2007 to 2024). "There are also hints of an overexpression of DKK1 in especially aggressive pancreatic adenocarcinomas." (PMID 27539223, 2016). "Notably, CCR5 ligands Ccl3 and Ccl4 are upregulated when DKK1 is expressed and have previously been shown to be strong mediators of Treg infiltration in pancreatic adenocarcinoma." (PMID 35924447, 2023). "However, in contrast to the extracellular Wnt antagonists such as DKK1 and sFRPs, which are suppressed in certain tumors, the Sulfs are upregulated in pancreatic adenocarcinomas and exert a positive effect on Wnt signaling." (PMID 17460759, 2007). "Various studies also demonstrated the effect of DKK1 on the prognosis of certain cancers, such as head and neck squamous carcinoma (HNSC), NSCLC, and pancreatic adenocarcinoma (PAAD)." (PMID 34899842, 2021).
psoriatic arthritis (6 papers, 2017 to 2024). Joint inflammation associated with psoriasis. "Overall, immunohistochemical reactivity for TGF-β1 in synovial tissue was elevated in patients with psoriatic arthritis (p = 0.024) and was positively correlated with IL-17A (r = 0.355, p = 0.024) and Dkk1 (r = 0.444, p = 0.004)." (PMID 38672170, 2024). "IHC reactivity for TGF-β1 in the synovial tissue was higher in patients with psoriatic arthritis (p 0.036) and was positively correlated with IL-17 A (r = 0.389, p = 0.012), and Dkk1 (r = 0.388, p = 0.012)." (PMID 36997896, 2023). "The English terms: ‘DKK1’, ‘Dickkopf-1’ ‘Dickkopf related protein 1’, ‘psoriatic arthritis’ and ‘PsA’ were used for search purposes." (PMID 37750896, 2023). "The IHC reactivity for TGF-β1 in the synovial tissue was higher in patients with psoriatic arthritis (p 0.010) and was positively correlated with IL-17 A (r = 0.389, p = 0.012) and Dkk1 (r = 0.388, p = 0.012)." (PMID 36997896, 2023). "Higher DKK1 level was found to be associated with higher disease severity (p < 0.001) as well as PsA Disease Activity Score (PASDAS) (p < 0.001), Simplified Psoriatic Arthritis Radiographic Score (SPARS) (p < 0.001) and PsA Impact of Disease (PsAID) (p = 0.001)." (PMID 37750896, 2023). "TGF-β1 (which is necessary for the activation of Th17 cells, but also involved in regeneration processes) immunoreactivity in synovial tissue, was higher in patients with erosive psoriatic arthritis in relation to the increased levels of IL-17 A and Dkk1 in the IHC." (PMID 36997896, 2023). "A recent systematic review identified four candidate serum-soluble bone-turnover biomarkers (dickkopf-1, Dkk-1; macrophage-colony stimulating factor, M-CSF; matrix metalloproteinase-3, MMP-3; osteoprotegerin, OPG) showing possible association with psoriatic arthritis (PsA)." (PMID 28934972, 2017). "The IHC reactivity of TGF-β1 in synovial tissue was higher in patients with erosive psoriatic arthritis, and TGF-β1 was in relation to higher levels of gene expression of IL-17 A and Dkk1." (PMID 36997896, 2023).
sarcoma (6 papers, 2007 to 2025). A usually aggressive malignant neoplasm of the soft tissue or bone. "Previously we demonstrated that expression of human Dkk-1 by the chondroblastic OS sarcoma cell line MOSJ (MOSJ-Dkk-1 cells) resulted in accelerated tumour growth and an aggressive osteolytic phenotype." (PMID 35277659, 2022). "Genes including Wnt 4 and 5a, beta-catenin, LEF1, and RhoA in Wnt-signaling pathways showed significantly lower expression and DKK1, a Wnt signal inhibitor showed strong expression in both sarcomas, while those in Hedgehog pathways showed higher expression in both sarcomas, especially Gli1." (PMID 22852096, 2012). "Thus, to directly address whether constitutive Wnt pathway activation in these sarcoma lines involved an autocrine Wnt signaling loop, we took advantage of the DKK1 and FRP1 antagonists." (PMID 25999350, 2015). "The expression of Dkk-1 by two OS cell lines; MG63, a well-characterised osteogenic sarcoma and LS1, a cell line derived from an excised OS, was examined in more detail in tissue culture experiments." (PMID 17987039, 2007).
Spondyloarthritis (6 papers, 2015 to 2023). "Significantly higher serum DKK-1 levels were correlated with disease duration in patients with early spondyloarthritis, and the serum DKK-1 levels were also found to be correlated with disease duration." (PMID 37261370, 2023). "The German Spondyloarthritis Inception Cohort (GESPIC) study reported that patients with lower Dkk1 levels were more prone to develop syndesmophytes than those with higher levels." (PMID 28882159, 2017). "The role of dickkopf-related protein 1 (DKK-1) in radiographic development may become a robust marker for early spondyloarthritis (SpA) diagnosis." (PMID 37261370, 2023). "DKK1 has potential as a biomarker for spondyloarthritis (SpA)." (PMID 38033331, 2023). "Dickkopf-1 (Dkk-1) is a key regulator of bone remodeling in spondyloarthropathies." (PMID 35743102, 2022).
triple-negative breast carcinoma (6 papers, 2012 to 2024). An invasive breast carcinoma which is negative for expression of estrogen receptor (ER), progesterone receptor (PR), and human epidermal growth factor receptor 2 (HER2). "In women with triple-negative breast cancer, which is associated with a high risk of recurrence, expression of DKK-1 indicated poor outcome of patients." (PMID 24528599, 2014). "Immunohistochemistry was used to characterize the expression pattern of DKK1 and beta-catenin in 85 triple negative breast cancers and prognostic significance was assessed by Kaplan-Meier analysis and Cox proportional hazards regression modeling." (PMID 22649545, 2012). "Up-regulation of DKK1 in our study correlated with cytoplasmic/nuclear beta-catenin accumulation in triple negative breast cancers (p = 0.000)." (PMID 22649545, 2012). "We investigated the prognostic importance of dickkopf-1(DKK1) and beta-catenin expression in triple negative breast cancers." (PMID 22649545, 2012). "Expression of DKK1 in triple negative breast cancers correlated with cytoplasmic/nuclear beta-catenin (p = 0.000)." (PMID 22649545, 2012). "We therefore determined whether the autonomous compression of enriched BCSCs, which was regulated by BCSC-derived DKK1, exerted a role in cancer metastasis by using triple-negative breast cancer (TNBC) cell lines." (PMID 35296660, 2022). "DKK1 together with beta-catenin might be important prognostic factors in triple negative breast carcinoma." (PMID 22649545, 2012). "Therefore, it might be helpful to integrate the DKK1 expression status with the tumor stage to help predict the prognosis of triple negative breast cancers, although the cases in other stages were too small to detect its prognostic significance." (PMID 22649545, 2012). "Our data, which revealed a upregulation of AXIN2, DKK1 and MYC in the TamR cells, are largely consistent with findings documented in current literature on triple negative breast cancer." (PMID 23547709, 2013).